NCOA6 (nuclear receptor coactivator 6)
Diseases named in the same sentence as NCOA6 in open-access papers:
NCOA6 is named in the same sentence as 26 diseases in open-access papers, as found by Europe PMC text mining. Sharing a sentence is not in itself a finding about the gene and the disease. The quoted sentences say what the papers report.
breast cancer (6 papers, 2010 to 2025). A primary or metastatic malignant neoplasm involving the breast. "Taken together, using GC-Mass spectroscopy approach provides a different perspective in shedding light on the mechanism of breast cancer and identifying some of the genes that are associated with breast cancer pathogenesis (such as NCOA6) that could potentially be biomarkers for breast cancer." (PMID 31511569, 2019). "Nuclear receptor coactivator 6 (NCoA6), located on the 20th human chromosome, was first identified in breast cancer." (PMID 37553876, 2023). "In addition, it is worth investigating the role of other genetic biomarkers identified through the GC-Mass spectroscopy data from this study, such as NCOA6 which may identify some of the environmental links to breast cancer such as stress or abnormal sleep patterns." (PMID 31511569, 2019).
breast tumors (2 papers, 2020 to 2023). "NCOA6 is also known as AIB3, a commonly amplified gene in breast tumors." (PMID 37491298, 2023).
pancreatic cancer (2 papers, 2023 to 2025). "Our study revealed the role of NCOA6 in the ferroptosis of pancreatic cancer cells by knocking downNCOA6 in pancreatic cancer cells and exploring the ferroptosis of these cells." (PMID 40065720, 2025). "We found that NCOA6 can affect the expressions of SCD1 and ACSL4 in pancreatic cancer cells.NCOA6 knockdown upregulated the expression of ACSL4 and downregulated the expression of SCD1." (PMID 40065720, 2025). "NCOA6 knockdown in pancreatic cancer cells results in the downregulation of ACSL4 and the upregulation of SCD1, thus enhancing the lipid peroxidation caused by RSL3 in pancreatic cancer cells and increasing their sensitivity to ferroptosis." (PMID 40065720, 2025). "Here, we show that knocking down the nuclear receptor co-activator,NCOA6, enhances the sensitivity of pancreatic cancer cells to ferroptosis." (PMID 40065720, 2025). "The results revealed that NCOA6 expression was positively related to SCD1 expression in pancreatic cancer tissues and negatively related to ACSL4 expression." (PMID 40065720, 2025). "Our study revealed that the NCOA6 gene regulates the sensitivity of pancreatic cancer cells to oxidative stress by influencing SCD1 and ACSL4." (PMID 40065720, 2025). "In vitro, NCoA6 expression levels in eight human pancreatic cancer cell lines were much higher than those in normal human pancreatic ductal epithelium H6C7 cells." (PMID 37553876, 2023). "Relationship between clinicopathological features and NCoA6 expression in patients with pancreatic cancer." (PMID 37553876, 2023). "Pancreatic cancer sequencing data from TCGA and GTEx showed that NCoA6 expression was upregulated in 178 PAAD samples compared to 171 normal tissues." (PMID 37553876, 2023). "In summary, we demonstrated that NCoA6 is an oncogene involved in the progression of pancreatic cancer." (PMID 37553876, 2023). "This study reveals that targeting NCOA6 might alleviate gemcitabine resistance in pancreatic cancer." (PMID 40065720, 2025). "NCOA6 affects the sensitivity of pancreatic cancer cells to gemcitabine by increasing lipid oxidation, but the mechanism might be multifaceted." (PMID 40065720, 2025). "To verify the expressions of NCOA6, SCD1 and ACSL4 in patient tissues, we randomly selected 30 patients with pancreatic cancer from our center, and immunohistochemical staining was performed on their paraffin-embedded tissues with corresponding antibodies." (PMID 40065720, 2025). "We detected the protein expression level of NCOA6 in a pancreatic duct epithelial cell line (H6C7) and several pancreatic cancer cell lines." (PMID 40065720, 2025). "Mechanistically,NCOA6 knockdown promotes the expression of ACSL4 while inhibiting the expression of SCD1, resulting in changes in lipid metabolism, sensitivity to RSL3-induced ferroptosis, and sensitivity to gemcitabine in pancreatic cancer." (PMID 40065720, 2025).
acute tubular necrosis (1 paper, 2024). "Finally, with bioinformatics, in vitro, and in vivo data on the direct role of NCOA6 in the innate immune response and diseases, we suggest NCOA6 as a new therapeutic target for NLRP3-dependent diseases, including gouty arthritis and acute tubular necrosis." (PMID 38195836, 2024).
Arthritis (1 paper, 2024). Inflammation of a joint. "Using loss-of-function mouse models, we clearly showed that NCOA6, particularly myeloid NCOA6, has critical functions in promoting NLRP3 inflammasome-mediated inflammatory diseases, including FA-induced ATN and MSU crystal-induced arthritis." (PMID 38195836, 2024). "Genetic ablation of Ncoa6 substantially attenuated the severity of FA-induced ATN and MSU crystal-induced arthritis in mice and decreased IL-1β and active caspase-1 levels." (PMID 38195836, 2024). "Consistent with the in vitro data, these in vivo data suggest that NCOA6 is necessary for NLRP3-dependent inflammatory diseases, including FA-induced ATN and MSU crystal-induced arthritis." (PMID 38195836, 2024). "As in FA-induced ATN, the severity of MSU crystal-induced arthritis was significantly diminished in Ncoa6+/− mice 24 h after MSU injection, as assessed by the Δ thickness of the paw and ankle, which was decreased in the Ncoa6+/− mice." (PMID 38195836, 2024). "When Ncoa6fl/flLysMCRE mice were subjected to MSU crystal-induced arthritis, they exhibited substantial attenuation of joint swelling compared to that of Ncoa6fl/fl mice as early as 3 h after MSU injection, and this response was more pronounced than that in Ncoa6-haploinsufficient mice." (PMID 38195836, 2024). "In sharp contrast, mice with and without complete Freund’s adjuvant (CFA)-induced arthritis, which is not NLRP3 inflammasome-specific, showed no such difference in the thickness of the paw and ankle, indicating that NCOA6 may specifically contribute to gouty arthritis in vivo." (PMID 38195836, 2024).
cataract (1 paper, 2020). Partial or complete opacity of the crystalline lens of one or both eyes that decreases visual acuity and eventually results in blindness. "A novel variant in the gene NCOA6 (p.Gly597Asp), hitherto not known to be linked with human cataracts, was documented in this family." (PMID 33339270, 2020).
congenital cataracts (1 paper, 2020). "In the present study, for the first time, a variation (Gly597Asp) was identified in NCOA6 associated with human congenital cataracts, along with hearing and speech impairments." (PMID 33339270, 2020). "This study also documented mutations in a novel gene, NCOA6, to be a putative gene for syndromial congenital cataracts and associated hearing and speech impairments." (PMID 33339270, 2020).
dependent (1 paper, 2024). "Genetic ablation of Ncoa6 substantially attenuated the severity of two NLRP3-dependent diseases, folic-induced acute tubular necrosis and crystal-induced arthritis, in mice." (PMID 38195836, 2024).
gouty arthritis (1 paper, 2024). "Overall, the transcriptome data suggest that NCOA6 is a key regulator dictating the pathological activation of macrophages in gouty arthritis." (PMID 38195836, 2024). "To further probe the pathological relevance of NCOA6, we established an in vivo model of gouty arthritis in mice (MSU crystal-induced arthritis), which is another representative model of NLRP3-dependent inflammatory disease." (PMID 38195836, 2024). "In the present study, the transcriptome, qRT‒PCR, immunofluorescence, and immunohistochemistry data using macrophages and synovia of gout patients suggest that NCOA6 is a key regulator of gouty arthritis, confirming our major findings in the human system." (PMID 38195836, 2024). "These decreases in arthritic severity and inflammatory cell infiltration were almost completely reversed by the intra-articular injection of recombinant IL-1β into the affected joints, demonstrating the decisive role of the myeloid NCOA6–IL-1β axis in NLRP3-dependent gouty arthritis." (PMID 38195836, 2024). "Moreover, immunohistochemical staining revealed that NCOA6 expression was upregulated in the synovial tissues of gout patients compared to those of osteoarthritis (OA) patients, who served as a control." (PMID 38195836, 2024). "Moreover, NCOA6 expression was elevated in the synovial macrophages of patients with gouty arthritis, correlating with IL-1β expression." (PMID 38195836, 2024). "Therefore, we finally wondered whether NCOA6 is involved in the mechanism of approved anti-gout drugs, including allopurinol, febuxostat, dexamethasone, and colchicine, all of which have been commonly prescribed for gout patients." (PMID 38195836, 2024). "Conclusively, NCOA6 is a critical regulator of NLRP3 inflammasome activation and is therefore a promising target for NLRP3-dependent diseases, including gout." (PMID 38195836, 2024). "In this context, targeting the NLRP3 ATP hydrolysis motifs (Walker A and B) may hold promise in alleviating NCOA6-induced NLRP3 hyperactivation and could be a novel treatment strategy for inflammatory diseases dependent on NLRP3, including gouty arthritis." (PMID 38195836, 2024). "To ascertain the clinical relevance of NCOA6 as a critical regulator of the NLRP3 inflammasome, we profiled global gene expression in synovial fluid macrophages freshly isolated from gouty arthritis patients (n = 4) in comparison with peripheral blood monocytes from healthy donors (n = 4)." (PMID 38195836, 2024). "Consistent with RNA sequencing data in gout macrophages, NCOA6 expression in peripheral human monocytes of healthy donors was upregulated in response to the administration of MSU crystals, which are frequently detected inside gout macrophages." (PMID 38195836, 2024). "Furthermore, NCOA6 speck formation in THP-1 cells stimulated with LPS + MSU was markedly decreased by colchicine, indicating that the anti-gout activity of colchicine might occur via the blockade of NCOA6 expression and/or speck formation." (PMID 38195836, 2024). "Notably, among approved anti-gout drugs, colchicine completely abrogated NCOA6 expression and speck formation in activated macrophages, suggesting that colchicine inhibits NLRP3 inflammasome activity by targeting NCOA6." (PMID 38195836, 2024). "Interestingly, the cytoplasmic colocalization of NCOA6 with ASC was also noted in neutrophils in the synovial fluid of gout patients, another type of innate immune cell critically involved in gouty arthritis, suggesting that this colocalization is not unique to macrophages." (PMID 38195836, 2024).
Hearing impairment (1 paper, 2020). A decreased magnitude of the sensory perception of sound. "It is therefore tempting to speculate that the variation G597D might interfere with the interaction between NCOA6 and TRα / TRβ, thereby causing hearing impairment in the affected subjects." (PMID 33339270, 2020).
liver cancer (1 paper, 2023). An epithelial or non-epithelial malignant neoplasm that arises from the liver. "For example, NCoA6 overexpression has been demonstrated in liver cancer compared to ANTs and is closely correlated with poor prognosis." (PMID 37553876, 2023). "NCoA6 is highly expressed in many cancers, including colorectal cancer, liver cancer, and melanoma." (PMID 37553876, 2023).
lymph node metastasis (1 paper, 2023). "Our study showed that there was no statistic difference of the status of lymph node metastasis and distant metastasis between high and low NCoA6 expression groups, which may be due to the small number of patients that already had metastasis at the time of diagnosis." (PMID 37553876, 2023).
melanoma (1 paper, 2024). A malignant, usually aggressive tumor composed of atypical, neoplastic melanocytes. "EP400, Mi-2β, PRDM4, NCOA6 or CARM1 silencing significantly induced the response to T-cell attack in melanoma cells, and led to more than 20% of the melanoma cells to be eliminated by T-cell-mediated killing." (PMID 38461299, 2024).
pancreatic ductal adenocarcinoma (1 paper, 2023). An infiltrating adenocarcinoma that arises from the epithelial cells of the pancreas. "However, the role of NCoA6 in pancreatic ductal adenocarcinoma (PDAC) remains unclear." (PMID 37553876, 2023).
peritonitis (1 paper, 2024). Inflammation of the peritoneum (tissue that lines the abdominal wall and covers most of the organs in the abdomen). "To this end, we assessed Ncoa6 expression in mouse models of acute inflammation (acute peritonitis) and chronic inflammation (collagen-induced arthritis)." (PMID 38195836, 2024).
pulmonary hypertension (1 paper, 2022). Increased pressure within the pulmonary circulation due to lung or heart disorder. "The key pathogenic features of pulmonary hypertension are endothelial apoptosis and vascular inflammation, which are caused by the down-regulation of Amphiregulin, accompanied by HIF-1a and BAD-mediated up-regulation of the target genes such as RRP1B, PHB2, and NCOA6." (PMID 35732465, 2022).
rheumatoid arthritis (1 paper, 2024). A chronic, systemic autoimmune disorder characterized by inflammation in the synovial membranes and articular surfaces. "In mice with collagen-induced arthritis, a chronic arthritis model that mimics rheumatoid arthritis (RA), Ncoa6 expression was much higher in the synovial tissue of arthritic mice than that in the synovial tissue vehicle-treated control mice." (PMID 38195836, 2024).
cancer (10 papers, 2013 to 2024). A tumor composed of atypical neoplastic, often pleomorphic cells that invade other tissues. "NCoA6 is often overexpressed in various cancer types, and its overexpression levels are associated with poor prognoses for cancer patients." (PMID 37553876, 2023). "Moreover, NCOA6 has been implicated in the pathogenesis of diabetes mellitus, atherosclerosis, and some types of cancer, and innate immune cells, such as macrophages, are also involved in these diseases." (PMID 38195836, 2024). "Nuclear receptor coactivator 6 (NCoA6) is overexpressed in various cancers and considered a multifunctional coactivator of various transcription factors and nuclear receptors." (PMID 37553876, 2023). "The IHC staining results of clinical samples further confirmed the upregulation of NCoA6 in cancer tissues compared to ANTs (n = 55)." (PMID 37553876, 2023). "Nuclear receptor coactivator 6 (NCOA6), a coactivator, has been implicated in embryonic development, metabolism, and cancer pathogenesis, but its role in innate immunity and inflammatory diseases remains unclear." (PMID 38195836, 2024). "Therefore, we speculated that NCoA6 knockdown might arrest the cancer cell cycle, inhibit cell proliferation, and ultimately promote apoptosis." (PMID 37553876, 2023). "Our findings of NCoA6 could improve the understanding of molecular pathogenesis of PDAC and reveal novel prognostic and therapeutic targets for this cancer." (PMID 37553876, 2023). "Taken together, the co-expression of these genes (NCOA6, HDAC1, RB1) could play a role in various types of cancer." (PMID 34439147, 2021).
tumor (9 papers, 2013 to 2025). "The high-CMLHMS group exhibited upregulation of genes such as TRPC4AP, NUSAP1, EFNA1, KMT2A, and NCOA6, which are implicated in chromatin remodeling, cell proliferation, and tumor progression." (PMID 40144021, 2025). "Second, the causal relationship between the anti‐tumor effects of NCoA6 knockdown and the molecular changes observed in this study warrants further investigation." (PMID 37553876, 2023). "The high IHC score for NCoA6 correlated with tumor size and TNM stage." (PMID 37553876, 2023). "Therefore, targeting NCoA6 to inhibit tumor malignancy may be a novel therapeutic approach for PDAC." (PMID 37553876, 2023). "In silico analysis uncovered three putative miRNA targets in humans, namely the transcription factor 7 (TCF7), nuclear receptor coactivator 6 (NCoA6), and engrailed-2 (EN2), all upregulated in BC and exploiting their role in tumor initiation and progression." (PMID 39519491, 2024). "These combined approaches enabled the identification of six tumour suppressor driver genes—namely BAP1, CREBBP, FAT1, NCOA6, RAD21 and UBR5—as regulators of the DDR and maintenance of chromosomal stability in NSCLC." (PMID 39738653, 2024). "Further lasso regression analysis identified seven potential prognostic markers (IL27, CD1D, NCOA6, CTSE, FCGRT, CFHR1, and APOA2) of robustness, most of which are related to tumor development." (PMID 32518711, 2020). "Research has shown that NCOA6 is related to the invasion and metastasis of tumor cells, but the relationship between NCOA6 and ferroptosis has not yet been reported." (PMID 40065720, 2025). "Additionally, the results indicated that tumor purity was only significantly correlated with LIPT1 (cor = 0.176, p = 5.84 × 10−3), NCOA6 (cor = 0.302, p = 1.43 × 10−6) and PRPF4B (cor = 0.188, p = 3.06 × 10−3), respectively." (PMID 36552841, 2022).
NCOA6 also shares sentences with these, for which no sentence is quoted: acute myeloid leukemia (1 paper); Infertility (1); leukemia (1); lung carcinoma (1); osteoarthritis (1); sarcoma (1); skin disorder (1).